CD4 (CD4 molecule)
Diseases named in the same sentence as CD4 in open-access papers (continued):
Sharing a sentence is not in itself a finding about the gene and the disease.
malaria (continued). "Thus, applying this approach in human malaria may both uncover new vaccine targets and help us down‐select vaccine candidates that are more likely to drive robust antibody responses through TFH restimulation and long‐lasting CD8 T‐cell memory differentiation through DC‐integrated CD4 help." (PMID 28935714, 2017). "Based on the analysis of the study, in regions of sub-Saharan Africa with high HIV and malaria burden, administering daily cotrimoxazole to HIV-infected pregnant women regardless of CD4 cell count is the preferred strategy under most conditions." (PMID 28985732, 2017). "Of note, malaria patients also showed a higher percentage of Foxp3+CD4+ Tregs than healthy controls but frequencies of Foxp3+ Tregs and PD1+CTLA4+ CD4+ T cells did not correlate." (PMID 27802341, 2016). "The MACOMBA project will provide further information about the suitability of co-trimoxazole for malaria prevention among HIV-infected pregnant women, regardless of their CD4 count." (PMID 23945130, 2013). "Published reports in humans and mice have shown that CD4 and CD8 T cell responses against malaria or non-malaria antigens can be inhibited by malaria infections." (PMID 22205939, 2011). "Recent work has highlighted the importance of Tfh cells in immune resistance to blood-stage malaria, we then asked whether lack of RACK1 in CD4+ T cells resulted in phenotypic abnormality of the Tfh compartment." (PMID 39024388, 2024). "Although we identified CD4+ T cells along with many other immune cell populations as important sources of type I IFNs, we do not know the mechanism of type I IFN induction during malaria." (PMID 37781920, 2023). "Finally, the effects of CD4+ T cell STING activation on preexisting Th1 and Tr1 cells from individuals living in malaria-endemic areas were not evaluated." (PMID 37781920, 2023). "However, with a lowered immunity (lower mean CD4 count) among HIV-positive patients on ART and those not on ART, one would ordinarily expect a higher prevalence of malaria parasitaemia in these groups, but this was not the case in our study." (PMID 36483323, 2022). "IL-10-producing CD4+ T cells and CD20+ IgG+ B cells were increased post-vaccination regardless of the intervention, thus could not be specifically attributed to any malaria vaccine regimen." (PMID 35715803, 2022). "In addition, although the staining for some cells such as CD4+ and CD8+ T cells and B cells was not as ideal in the malaria cases, we were still able to distinguish between stained and unstained cells." (PMID 36014972, 2022). "The Plasmodium parasite-released homolog of the mammalian migration inhibitory factor (MIF) induces antigen-experienced CD4+ T cells into short-lived effector cells rather than memory cells through binding on its CD74 receptor in DCs and macrophages during blood-stage malaria." (PMID 34987497, 2021). "However, the absolute numbers of CD4+ and CD8+ T cells did not change significantly in malaria parasite infected as compared with control mice." (PMID 33298881, 2020). "Whether TGF-β also promotes TFH differentiation during murine malaria has not been tested, but TGF-β promotion of TFH differentiation has been shown in several systems including cultured human CD4+ T cells and in mice infected with influenza virus." (PMID 32043415, 2020). "Therefore, the CD4/CD8 ratio should not be used in this way in the presence of active clinical infections, particularly malaria." (PMID 26581890, 2015). "Because malaria infection can induce CD4+ T cell activation and lead to the replication of HIV-1 in patients without ART, we postulated that malaria might activate resting CD4+ T cells, thereby promoting HIV-1 transcription and replication." (PMID 25487036, 2014). "Liver-stage malaria parasites inside hepatocytes occupy a cell type that can actively present antigen to MHC class I-restricted CD8+ T cells, but can neither directly activate CD4+ T cells, nor become licensed through interaction with CD4+ T cells." (PMID 25426113, 2014).
malaria (continued). "We found that the number of malaria-specific IFN-γ secreting T cells greatly diminished upon depletion of CD8+ T cells, but not CD4+ T cells, thus indicating that the majority of malaria-specific T-cell responses enhanced by 7DW8-5 in the NHPs were CD8+ T cells." (PMID 24205224, 2013). "At these time points, when the malaria parasitemia in the blood was undetectable, both the cellular frequencies and the MFI values of CD4 and CD8 T cell subsets of the BCG vaccinated and the BCG vaccinated, malaria infected mice were not significantly different." (PMID 22205939, 2011). "Interestingly, the breadth and magnitude of P. falciparum-specific antibody response in HIV+ individuals was not fully explained by the CD4+ T cell count and HIV viral load, suggesting that other factors play a role in generating robust antibody responses to malaria." (PMID 25928218, 2015). "Recent live attenuated malaria vaccination trials in humans and non-human primates as well as work in mice clearly demonstrate the requirement for protection of large quantities of IFN-γ producing CD8, CD4, and γδ T cells as well as IFN-γ secreting NK and NKT cells in the liver." (PMID 26074888, 2015). "The detection of both CD4+ and CD8+ HGXPRT reactive T cells and the absence of HGXPRT specific IgG responses in people with acute malaria indicates that natural exposure generates different immune responsiveness to that of the P. yoelii experimental murine malaria model." (PMID 19500406, 2009). "Accordingly, the aim of this study was to determine whether LCP constructs incorporating defined CD4+ and/or CD8+ T cell epitopes, with or without specific CD4+ T cell help, could induce epitope-specific immune response and protect against pathogen challenge in a rodent model of malaria." (PMID 22936972, 2012).
lymphoma (516 papers, 1991 to 2026). A malignant (clonal) proliferation of B- lymphocytes or T- lymphocytes which involves the lymph nodes, bone marrow and/or extranodal sites. "For example, mutations in TET2 and DNMT3A are frequently observed in CD4 + T-helper cell-derived lymphomas, such as angioimmunoblastic T-cell lymphoma." (PMID 41431105, 2025). "Adult T-cell leukemia/lymphoma is a highly aggressive mature CD4+CD25+FoxP3+ T-cell neoplasm associated with chronic HTLV-1 infection, which affects around 10 million people worldwide." (PMID 41020241, 2025). "Persistent HIV replication (≥100,000 copies/mL) and low CD4 counts (<50/μL) correlate with heightened lymphoma risk, emphasizing the need for strict cART adherence." (PMID 40361360, 2025). "This ecological shift parallels observations in HIV-associated lymphomas, where Anelloviridae expansion correlates with CD4+ T-cell depletion." (PMID 40768422, 2025). "Evidence from other lymphomas supports the prognostic role of T-cell subsets: in mantle cell lymphoma, low CD4+ T cell counts have been linked to poor prognosis." (PMID 41244913, 2025). "A low CD4 count is associated with more aggressive forms of lymphomas, with a low survival on 1-year follow-up." (PMID 40606992, 2025). "In terms of immunosuppression, findings from cohort studies indicate that higher levels of HIV viremia and a lower nadir of CD4 count are associated with an increased risk of developing lymphoma." (PMID 38339297, 2024). "Fortuitously, we detect a significant impact of IRF8 KO or mutation in an assay (CD4 DO-11.10 cells activation) in which the antigen loaded into the lymphoma cells was already processed (the OVA peptide)." (PMID 38996030, 2024). "In that study, MHCII expressing lymphoma cells were associated with a TME rich in a CD4+ T-cell population with a high cytotoxicity expression profile signature (CD4CTL), while the reverse was observed for cells expressing low levels of MHCII." (PMID 40809150, 2024). "Immunosuppression plays a notable role in the development of lymphomas, but the prognostic impact of CD4 in HIV‐associated lymphomas remains controversial." (PMID 37081761, 2023). "B and CD4+ T cells play essential roles in viral clearance; thus, patients with lymphoma patients, who have B and CD4+ T cell deficiencies, are unable to effectively and rapidly clear SARS-CoV-2, leading to a higher risk of disease exacerbation or death." (PMID 37860581, 2023). "They reveal TFH, TREG and TFR cells as T cell populations particularly sensitive to CARD11 signaling, and help to explain the recurrence of somatic GOF CARD11 mutations in aggressive human T-lymphomas arising from CD4, TREG and TFH cells." (PMID 36960072, 2023). "Consistent with the effects of PD-1 in inhibiting TCR signaling and also CD28 co-stimulation, PD-1 inhibition mildly increased Card11M365K/M365K CD4 T cell accumulation in vivo, but was nevertheless insufficient to cause CD4 lymphoma or lymphoproliferation." (PMID 36960072, 2023). "Treatment with pevonedistat resulted in delayed progression of A20 lymphoma tumors, associated with increased CD4+ and CD8+ T-cell infiltration." (PMID 37031300, 2023). "Loss of CTSS activity reduces lymphoma growth by limiting communication with CD4 T follicular helper cells while inducing antigen diversification and activation of CD8 T cells." (PMID 34923982, 2021). "FOXP3 is traditionally used as a marker of CD4+ regulatory T-cells (T-reg), which were already implicated on immune suppression and worse prognosis of other lymphoma subtypes, such as follicular lymphoma." (PMID 33648463, 2021). "MD is a highly contagious and lymphoproliferative neoplastic disease, causing CD4+ T lymphoma in chicken." (PMID 34205549, 2021). "Human T-cell leukemia virus type 1 (HTLV-1) infects primarily CD4+ T-lymphocytes and evoques severe diseases, predominantly Adult T-Cell Leukemia/ Lymphoma (ATL/L) and HTLV-1-associated Myelopathy/ Tropical Spastic Paraparesis (HAM/TSP)." (PMID 32912211, 2020).
lymphoma (continued). "Using this model, we discovered that an LMP1-deleted EBV mutant causes activated DLBCLs in vivo because CD40L-expressing CD4 T cells in the tumor microenvironment can substitute for LMP1 in lymphomas with type III latency that express EBNA2." (PMID 32542010, 2020). "PBMCs derived from HIV-positive subjects with advanced HIV disease and lymphoma showed a loss of production of TNFα, IFNγ+, and IL-2 by CD4+ T cell sub-populations in EBV-stimulated cultures." (PMID 33102204, 2020). "Remarkably, most of the AITL patients carrying the RHOAG17V mutation also have TET2 mutations indicating a cooperation between these two mutations in disrupting normal CD4 T-cell phenotype and function in this aggressive lymphoma." (PMID 32796826, 2020). "In conclusion, HIV+ patients with lymphoma have a loss of CD4+ and CD8+ T cells subpopulations that are vital for the response and control of EBV infection." (PMID 30337929, 2018). "On the other hand, patients with lymphoma exhibited a loss of functional EBV-specific CD4+ T cells, as demonstrated by TNF-α+ (p = 0.008); IFN-γ+ (p = 0.025); and IL-2+ (p = 0.009) counts." (PMID 30337929, 2018). "Eighty percent of the HIV-associated lymphoma patients who died had baseline CD4+ T cell counts ≤200 cells/μl (p = 0.03)." (PMID 28592989, 2017). "Marek’s Disease Virus (MDV) is an alphaherpesvirus that infects chickens, transforms CD4+ T cells and causes deadly lymphomas." (PMID 29267390, 2017). "Virulent MDV strains cause immunosuppression and efficiently transform CD4+ T cells resulting in deadly lymphoma." (PMID 29267390, 2017). "The mean CD4 count in patients with HL was higher than that in patients with other lymphomas, implying that the frequency of HL is associated with ART and immune reconstitution syndrome in HIV-1-infected patients." (PMID 24407967, 2014). "Increased levels of CCL17 and/or CCL22 are also associated with higher frequencies of CD4+Foxp3+ T cells in cerebral spinal fluid of patients with lymphomatous and carcinomatous meningitis, gastric, and esophageal squamous cell carcinomas." (PMID 23874342, 2013). "A long lasting CD4 cell decline together with increased EBV load seems to be an indicator of lymphoma risk." (PMID 23880011, 2013). "Regarding the 3 main biological factors associated with a risk of lymphoma, a low C4 and a CD4/CD8 ratio lower than 0.8, were significantly more frequent in patients with a history of lymphoma and there was a trend towards an association with cryoglobulinemia." (PMID 23717383, 2013). "Human T-cell leukemia virus type 1 (HTLV-1) is the pathogen that causes the aggressive and lethal malignancy of CD4+ T-lymphocytes called adult T-cell leukemia/lymphoma (ATLL)." (PMID 23762762, 2012). "Indeed, complementation with WT LY9 via lentiviral transduction, unlike empty vector (EV), was sufficient to promote IFN-γ secretion induced by THP-1 plus HKMTb plus CytoStim in LY9-deficient CD4+ T-blasts or LY9 KO HuT78 T-lymphoma cells." (PMID 40446017, 2025). "However, even with cART, immune dysregulation persists, and low CD4+ T-cell counts in PWH remain associated with a heightened risk of lymphoma subtypes such as BL, DLBCL, PEL, and PCNSL, often linked to co-infection with EBV and KSHV." (PMID 41148820, 2025). "However, encouraging trends such as tele-pathology, introduction of IHC, and adaptation of flow cytometry machines beyond their use for CD4 counts to immunophenotyping lymphoma were shown to improve diagnostic accuracy in some regions." (PMID 39417984, 2025). "A few groups have reported the prognostic significance of CD4 in HIV‐associated lymphomas." (PMID 37081761, 2023). "Human T-cell leukemia virus-1 (HTLV-1) is a retrovirus that persistently infects CD4+ T-cells, and is the causative agent of adult T-cell leukemia/lymphoma (ATLL), tropical spastic paraparesis/HTLV-1-associated myelopathy (TSP/HAM) and several inflammatory diseases." (PMID 36072598, 2022).
lymphoma (continued). "Furthermore, some studies considered that the degree of immunosuppression with median lymphocyte CD4 count (< 200 cells/mm3) is proportional to the risk of developing lymphoma." (PMID 35896979, 2022). "Furthermore, CD70+ lymphoma B cells have been shown to partially contribute to Foxp3 expression in intratumoural CD4+CD25− T cells and thus the associated regulatory activity." (PMID 36471481, 2022). "However, frequencies of some, mostly low immunogenic EBV-associated lymphomas remain high after CD4+ T cell count stabilization due to anti-retroviral treatment (ART) in HIV patients." (PMID 34778072, 2021). "In lymphoma, sIL-2Rα may present IL-2 in vitro to CD4 + T cells and cause the differentiation of these cells into FoxP3 + Treg cells, resulting in the suppression of CD8 + T cells." (PMID 32660627, 2020). "There is strong evidence that HIV may directly drive lymphomagenesis but also HIV viremia and depth of CD4 nadir increase lymphoma risk." (PMID 32803474, 2020). "CD4 counts were also associated with EBV positivity in lymphomas." (PMID 24407967, 2014). "The low CD4 nadir in DART participants (10% had pre-ART CD4 <10 cells/mm3) may have contributed to this, with patients at long-term risk for events such as lymphoma, despite immune reconstitution." (PMID 23437399, 2013). "However, an ICOS antagonist demonstrated a 44% response rate in angioimmunoblastic T‐cell lymphoma; ICOS is highly expressed on T‐follicular helper cells (type of CD4 cell) and proliferation of these cells may be a pathogenic mechanism for these lymphomas." (PMID 41474629, 2026). "Furthermore, in contrast with the finding that Tfh cells may support the survival of lymphoma B cells, high numbers of IF CD4+PD1hi cells were associated with prolonged EFS in our analysis, which is consistent with another work by Smeltzer and Colleagues." (PMID 37373066, 2023). "However, this has mainly been observed in lymphomas, and, in our study, the nadir CD4 count associated with cancer could be many years before the incident cancer diagnosis." (PMID 33094910, 2020). "Collectively, these findings identified the BAMBI‐Wnt‐TGF‐β axis as a novel pathway by which HBV results in the CD4+ T cell exhaustion in lymphoma." (PMID 41492119, 2026). "Self-reactive B lymphoma cells are helped by CD4+ T cells that recognize a lymphoma neoantigen, an MHC class II-presented Idiotypic (Id) peptide (Signal 2)." (PMID 41741475, 2026). "Building on these insights, our study extended the concept to lymphoma, identifying miR‐19a‐3p as a novel HBx‐regulated miRNA that directly modulated CD4+ T cell function in DLBCL." (PMID 41492119, 2026). "Consistent with the predicted ligand–receptor signalling, TGFBR2 knockdown in CD4+ T cells increased HBx‐overexpressing lymphoma cell apoptosis, while reducing CD4+ T cell apoptosis and enhancing proliferation and effector cytokine secretion." (PMID 41492119, 2026). "Collectively, these data demonstrated that miR‐19a‐3p potentiates CD4+ T cell‐mediated tumour surveillance and suppresses HBx‐driven oncogenic progression in both syngeneic and human xenograft lymphoma models." (PMID 41492119, 2026). "UMAP analysis identified 25 clusters, and consistent with traditional gating, lymphoma patients showed reduced frequencies of naive CD4 + and CD8 + T cells (clusters 2,11, and 3)." (PMID 40630518, 2025). "Immune function markers such as CD4 counts are valuable prognostic indicators, as they reflect both the host’s capacity to tolerate chemotherapy and the biological aggressiveness of lymphoma in HIV-infected patients." (PMID 40606992, 2025). "Some in vitro experiments focused on B‐cell proliferative diseases confirmed that lenalidomide had various immunomodulatory effects on lymphoma B cells and CD4+CD25+ Tregs and regulated their interactions." (PMID 40458003, 2025).